ROCK2 (Rho associated coiled-coil containing protein kinase 2)
Diseases named in the same sentence as ROCK2 in open-access papers (continued):
Sharing a sentence is not in itself a finding about the gene and the disease.
colorectal cancer (9 papers, 2015 to 2023). A primary or metastatic malignant neoplasm that affects the colon or rectum. "TFAP2C inhibits Hippo signaling by upregulating ROCK1 and ROCK2 in colorectal cancer, thereby contributing to the stemness of colorectal cancer cells and the resistance to 5‐FU." (PMID 37799806, 2023). "In colorectal cancer, the inhibition of ROCK2 expression triggers the initial polarization of the colon cancer cell line and induces cell invasion." (PMID 33153478, 2020).
glioblastoma (9 papers, 2014 to 2023). The most malignant astrocytic tumor (WHO grade IV). "Similar results were exhibited in glioblastoma cells where ROCK2 KD increased migration by increasing phosphorylation of Cdc42/Rac which regulates actin polymerization and thus plays a central role in cell migration." (PMID 36719899, 2023). "Although a potential role for RhoA, which has been shown to regulate glioblastoma radioresistance via survivin, and ROCK2 in radiation resistance has been suggested, their collective mechanism remains poorly understood." (PMID 35277915, 2022). "ROCK1 and ROCK2 have been shown to play opposing roles in glioblastomas, where the knockdown of ROCK2 was seen to enhance proliferation whereas the inhibition of ROCK1 was seen to decrease the proliferation of glioblastoma cells." (PMID 31488179, 2019). "There are two ROCK isoforms: ROCK1, which is upregulated in glioblastoma tissue compared to normal brain tissue, and ROCK2, which is also expressed in normal brain tissue." (PMID 24170433, 2014). "Evodiamine can inhibit cell proliferation by inhibiting PI3K/Akt signal to induce apoptosis and activate MAPK in pleomorphic glioblastomas and effectively inhibit the protein expression of Rho, ROCK1, and ROCK2." (PMID 34925530, 2021). "Glioblastoma cells treated with this drug combination showed reduced phosphorylation of Akt and ERK, and decreased protein expression of ROCK2 and Zyxin." (PMID 33407478, 2021). "ShRNA was used to downregulate ROCK1 and ROCK2 expressions in the D54MG and 86HG39 glioblastoma cell lines, and the effects on cell migration, proliferation, substrate-dependent migration, and signaling pathways were compared." (PMID 24170433, 2014).
pulmonary hypertension (9 papers, 2015 to 2025). Increased pressure within the pulmonary circulation due to lung or heart disorder. "Consistently, the selective loss of ROCK2 in vascular smooth muscle prevents development of chronic hypoxia‐induced pulmonary hypertension in mice, suggesting the causative relation of ROCK2 in this disease." (PMID 29749605, 2018). "Furthermore, heterozygous ROCK2 deficient mice showed reduced hypoxia-induced pulmonary hypertension (PH) while the ROCK2 overexpression transgenic model had more severe PAH compared to their littermates." (PMID 41377066, 2025). "The serum ROCK2 level in the pulmonary hypertension group was significantly higher than that in the control group (P < 0.05)." (PMID 29921927, 2018). "ROCK2 plays a leading role in pulmonary hypertension in the plateau region, so selective ROCK2 inhibitors will be more effective in improving pulmonary hypertension." (PMID 29921927, 2018). "In idiopathic pulmonary hypertension, ROCK2 is highly expressed in pulmonary arteries of patients and fasudil treatment induces acute pulmonary vasodilation." (PMID 29749605, 2018). "Finally, ROCK2 has been found in vascular smooth muscle cells and has shown to play a role in hypoxia-induced pulmonary hypertension in mice, yet another rare but important complication from SSRI use during pregnancy." (PMID 25611484, 2015). "Rock2 was suggested to be predominant in VSMC contractility and critical in the hypoxia-induced pulmonary hypertension." (PMID 31017969, 2019). "Further, elegant study from Shimokawa Laboratory showed that ROCK2 in vascular smooth muscle cell (VSMC) contributes to the pathogenesis of cardiovascular diseases, including pulmonary arterial hypertension." (PMID 30884801, 2019). "Currently, studies on the relationship between pulmonary hypertension and ROCK1 and ROCK2 were limited to lung tissue level." (PMID 29921927, 2018). "However, the study of pulmonary hypertension in the plateau region is limited, and the detection of serum ROCK1 and ROCK2 in pulmonary hypertension patients is much more convenient." (PMID 29921927, 2018). "Moreover, increased ROCK function was also found to be involved in pulmonary hypertension, and again transcription levels of ROCK1 were more markedly enhanced than transcription levels of ROCK2 in both rat and human." (PMID 26468005, 2015).
cervical cancer (8 papers, 2010 to 2025). A primary or metastatic malignant neoplasm involving the cervix. "Previous studies have shown that the expression of RhoA, ROCK-1, and ROCK-2 is significantly elevated in cervical cancer cells." (PMID 40655948, 2025). "RhoC GTPase together with its downstream regulator ROCK2 regulate the radiation response and supply the radio resistance in cervical cancer." (PMID 32443784, 2020). "Further experiments were thus directed to discern the role of ROCK2 as the downstream effector of RhoC in cervical cancer radioresistance." (PMID 31488179, 2019). "Our results confirm that overexpression of RhoC induces radioresistance in cervical cancer cells and ROCK2 is the downstream target of RhoC in radiation response." (PMID 31488179, 2019). "In vitro and clinical sample-based studies have been performed to understand its contribution to radiation response in cervical cancer and this is the first report to establish the role of RhoC and its effector ROCK2 in cervical cancer radiation response." (PMID 31488179, 2019). "We demonstrate that inhibition of ROCK2 sensitizes tumor cells to radiation therapy and that the RhoC-ROCK2 signaling pathway is of crucial importance in regulation of DNA repair in cervical cancer." (PMID 31488179, 2019). "Future work would aim at evaluating ROCK2 as a biomarker and therapeutic target in the context of radioresistance in cervical cancer and understanding the mechanistic of RhoC and ROCK2 in DNA repair regulation." (PMID 31488179, 2019). "Our data proposes a novel role of RhoC in cervical cancer radioresistance and presents evidence to support ROCK2 as the downstream effector of RhoC in radioresistance." (PMID 31488179, 2019). "To further confirm that ROCK2 is indeed important and regulates radioresistance in cervical cancer, we decided to use another approach to inhibit ROCK2 and observe the effect on cell survival." (PMID 31488179, 2019). "We further investigated if ROCK2 and RhoC physically interact with each other in the nuclear compartment of the cervical cancer cells." (PMID 31488179, 2019). "Combined, our findings suggest a non-canonical signaling pathway for RhoC which regulates radiation response in cervical cancer via ROCK2 mediated DNA repair regulation." (PMID 31488179, 2019). "ROCK2, an important signaling molecule, can promote cervical cancer metastasis by upregulating and activating the expression and function of moesin protein through RhoA/ROCK2 pathway." (PMID 24992025, 2014). "Taken together, we demonstrated that VEGF-C activated RhoA/ROCK-2/moesin cascade in cervical cancer cells, leading to the accelerated cancer cell migration and invasion." (PMID 20429915, 2010). "In this study, we investigated the effects of VEGF-C on actin cytoskeleton remodeling and on cervical cancer cell migration and invasion and how the actin-regulatory protein, moesin regulated these effects through RhoA/ROCK-2 signaling pathway." (PMID 20429915, 2010). "In this report, we investigated the role of RhoC and ROCK2 in radioresistance in cervical cancer." (PMID 31488179, 2019). "Thus, our study establishes that RhoC regulates radio-resistance in cervical cancer via ROCK2’s crosstalk with DNA repair assembly proteins, however the exact mechanism of regulation of ROCK2 by RhoC is still under investigation." (PMID 31488179, 2019). "Finally, findings herein strongly provide robust evidence, both clinical and cell line based, that RhoC and ROCK2 regulate radiation response and contribute to radioresistance in cervical cancer." (PMID 31488179, 2019). "And through the correlation analysis of the expressions of ECT2 and RHOA, ROCK1, and ROCK2 in cervical cancer samples in TCGA database, it was found that the expression of ECT2 was significantly positively correlated with RhoA, ROCK1, and ROCK2." (PMID 40655948, 2025). "Cervical cancer metastasis is promoted by VEGF-C upregulating and activating moesin protein through RhoA/ROCK-2 pathway." (PMID 32443784, 2020).
cervical cancer (continued). "Eventually, Y-27632 inhibited ROCK-2 and therefore impaired VEGF-C-induced moesin expression and phosphorylation in cervical carcinoma (SiHa) cell line." (PMID 32443784, 2020).
diabetic nephropathy (8 papers, 2021 to 2026). "Robust genetic evidence underscores the pathogenic role of ROCK2 in diabetic nephropathy." (PMID 41311514, 2026). "This comprehensive review consolidates current knowledge on the distinct pathophysiological roles of the ROCK isoforms, ROCK1 and ROCK2, in diabetic nephropathy, drawing on recent insights from both genetic and pharmacological studies." (PMID 41311514, 2026). "ROCK2 has emerged as a critical mediator of inflammation and fibrosis in the pathogenesis of diabetic nephropathy." (PMID 41311514, 2026). "ROCK2 plays a key role in diabetic glomerulosclerosis and an ROCK2 inhibitor was observed to attenuate glomerular fibrosis in diabetic kidney disease." (PMID 39273063, 2024). "In earlier loss-of-function studies, we demonstrated the crucial roles of ROCK2 in podocyte health in several proteinuric kidney disease models (i.e. diabetic nephropathy, obesity-induced glomerulopathy)." (PMID 38565675, 2024). "These ROCK2-driven pathways enhance the expression of extracellular matrix proteins, including fibronectin and collagen IV, which accumulate in the glomerular mesangium and contribute to the characteristic histopathological changes of diabetic nephropathy." (PMID 41311514, 2026). "This ROCK2-Notch axis induces podocyte apoptosis by upregulating pro-apoptotic factors and downregulating survival pathways, contributing to podocyte depletion—a key driver of albuminuria and glomerular scarring in diabetic nephropathy." (PMID 41311514, 2026). "In addition to the known beneficial effects of ROCK2 inhibition in diabetic nephropathy and a unilateral ureteral obstruction model, this study identified novel effects on FSGS." (PMID 38565675, 2024). "The ROCK2 protein levels were also elevated in db/db mice and high-fat diet (HFD)-fed mice, both of these are common type 2 diabetes models for studies of diabetic kidney disease." (PMID 35396346, 2022). "Previously, ROCK2 has been proved to promote mesangial proliferation and ECM production by strengthening the inflammatory process and fibrotic circuitry in diabetic nephropathy." (PMID 33936064, 2021).
liver cancer (8 papers, 2014 to 2022). An epithelial or non-epithelial malignant neoplasm that arises from the liver. "We show that ROCK2 is a novel target of celastrol and inhibition of ROCK2 suppresses elicited ezrin activation and liver cancer cell migration." (PMID 32647287, 2020). "Mechanistically, celastrol inhibits the ROCK2-mediated phosphorylation of ezrin at Thr567 which harnesses liver cancer cell migration." (PMID 32647287, 2020). "Here we show that ROCK2 is a novel target of celastrol and inhibition of ROCK2 suppresses elicited ezrin activation and liver cancer cell migration." (PMID 32647287, 2020). "B; 2a, b; 3a, b and 4a, b, positive staining rates of DLC-1, Rho A, ROCK2 and moesin in liver cancer tissue samples were 38.75, 78.75, 75.00 and 86.25 % respectively, which was significantly different from those in normal mucosa (83.75, 43.75, 40.00 and 66.25 %) (P < 0.001)." (PMID 26846339, 2016). "Comparing normal liver tissue samples (225 patients) and liver hepatocellular carcinoma (LIHC) samples (371 patients), the expression of the genes: RhoA, Rac1, LIMK1, LIMK2, ROCK1, ROCK2, MLCK2, and PAK4 is upregulated in liver cancer." (PMID 35241781, 2022). "Depletion of HK2/ROCK2 by shRNA or inhibitors reduces TPC contractility to remodel vasculature, while combined treatment of HK2 inhibitor and doxorubicin enhanced the efficacy of chemotherapy drug against tumor growth in both lung and liver cancer animal models." (PMID 34650057, 2021). "Moreover, GASC1 inhibition may provide a much-needed treatment option for tumors that stably express ROCK2, as well as other antiapoptotic BCL2 family members that mediate resistance to liver cancer chemotherapy." (PMID 33692332, 2021).
melanoma (8 papers, 2015 to 2024). A malignant, usually aggressive tumor composed of atypical, neoplastic melanocytes. "In a number of cancers (breast, bladder, liver, melanoma and others) the ROCK2 pathway is implicated in the metastatic process." (PMID 28554330, 2017). "The elevated expression of ROCK2 in primary melanomas with metastasis was further confirmed by IHC staining, using anti-ROCK2 antibody." (PMID 39039072, 2024). "Specifically, PRKDC amplification coupled with CDK4 amplification increased cell proliferation in S-II, whereas ROCK2 amplification elevated the increased angiogenesis and promoted melanoma metastasis in S-III." (PMID 39039072, 2024). "Deletion of Rock1 appears to increase tumor burden in the NSCLC model, whereas deletion of Rock2 leads to decreased tumor onset and survival in the melanoma model." (PMID 26765561, 2016). "ROCK2 functions as a key downstream effector of RhoA small GTPase to play a critical role in the oncogenesis of prostate, bladder, fibrosarcoma, melanoma, liver and lung cancer." (PMID 27229528, 2016). "Collectively, our data illustrated that the elevated amplification of ROCK2 in the S-II subgroup could be responsible for the elevated angiogenesis and might serve as a possible predictive marker for melanoma metastasis." (PMID 39039072, 2024). "Accordingly, while the loss of either Rock1 or Rock2 had no negative impact on tumorigenesis in mouse models of non-small cell lung cancer and melanoma, loss of both blocked tumor formation, as no tumors arise in which both Rock1 and Rock2 have been genetically deleted." (PMID 26765561, 2016). "However, incomplete or specific inhibition of only one isoform of ROCK alone may not be an effective treatment, and may even lead to adverse results as our results also highlight isoform specific tumor suppressive functions for ROCK1 in lung and ROCK2 in melanoma models." (PMID 26765561, 2016). "To further confirm that the ROCK2 (kinase)-HMGB1 TF-PDGFRA TG cascade promotes tumor metastasis, we constructed an independent validation cohort including 20 melanoma patients and collected matched primary and metastatic melanoma tumor samples for proteomic and phosphoproteomic analysis." (PMID 39039072, 2024). "However, this aspect may be somewhat tissue-dependent, as, for example, in non-small cell lung cancer and melanoma, only targeting both ROCK1/ROCK2 was able to prevent tumor growth." (PMID 35406401, 2022).
asthma (7 papers, 2017 to 2025). "All analyzed proteins were expressed in the bronchial smooth muscle, with a significant increase in the expression of RG1 and ROCK2 in guinea pigs from the asthma model compared to control guinea pigs (p < 0.01; n = 5 per group)." (PMID 41463119, 2025). "Together, SUMOylation-mediated ROCK2 activation is an integral component of Rho/ROCK signaling in regulating the pathological conditions of asthma and thus SUMOylation is an additional target for the therapeutic intervention of this disease." (PMID 37393345, 2023). "In the mouse model of asthma, Rock1+/− and Rock2+/− mice showed attenuated mast cell degranulation and reduced number of eosinophils, but both developed unaffected lung inflammation." (PMID 32178482, 2020). "Moreover, given the high degree of conservation of the RG1 and ROCK2 signaling pathways between rodents and humans, these findings may be extrapolated to human airway physiology, underscoring their potential relevance to the pathophysiology of asthma." (PMID 41463119, 2025). "Interestingly, although immunohistochemical analysis revealed no changes in MYPT1 expression or its phosphorylated forms in the bronchial smooth muscle of guinea pig asthma model, both RG1 and ROCK2—but not ROCK1—showed significantly increased expression levels." (PMID 41463119, 2025).
bladder cancer (7 papers, 2014 to 2022). "Elevated ROCK2 protein expression levels have also been reported in colon and bladder cancers and are associated with shorter disease-free survival in patients with bladder cancer." (PMID 26377148, 2016). "Strong cytoplasmic anti-ROCK2 reactivity was observed in normal bladder epithelium as well as in bladder carcinoma." (PMID 28554330, 2017). "Cell migration of macrophages and bladder cancer cells may inhibit ROCK2 expression." (PMID 36187824, 2022).
memory impairment (7 papers, 2021 to 2022). "Loss of miR-135a-5p expression results in an increase in Rock2 activity and hyperphosphorylation of Add1 at Ser726, which in turn leads to dendritic abnormalities and memory impairments." (PMID 33771994, 2021). "Artificial inhibition of miR-135a-5p results in synaptic disorder and memory impairments via activation of the Rho-associated coiled-coil containing protein kinase 2 (Rock2)/Adducin 1 (Add1) signaling pathway." (PMID 33771994, 2021). "As Rock2 accumulates in the earliest stages of AD and remains elevated throughout the disease progression, our data set the basis for a future development of therapeutic strategies to overcome neuronal loss and memory impairment in AD." (PMID 35496276, 2022). "Given that Rock2 accumulates in the neurons of early-stage human AD brain and is associated with AD hallmarks, our data showing efficacy of the Rock2 inhibitor, compound SR3677, against Aβ25-35 memory impairment in mice should be considered as a potential therapeutic approach in AD." (PMID 35496276, 2022).
myocardial infarction (7 papers, 2018 to 2026). Gross necrosis of the myocardium, as a result of interruption of the blood supply to the area, as in coronary thrombosis. "High levels of ROCK2 have been seen in mice with myocardial infarction, whereas ROCK2 is significantly reduced with the post-infarction exercise (8 weeks)." (PMID 36036015, 2022). "Data from experimental animal models showed that complete or partial deletion of Rock1 or Rock2 protected mice from fibrosis during hypertensive cardiac remodelling and following myocardial infarction." (PMID 32178482, 2020). "Prior studies have shown that ferulic acid attenuates the migratory and proliferative capacity of cardiac fibroblasts and reduces myocardial fibrosis after myocardial infarction by inhibiting the pRB-E2F1/CCNE2 and RhoA/ROCK2 pathways." (PMID 38254195, 2024). "The reducing rate of TFR in myocardial infarction area, RhoA activity, and ROCK1, ROCK2, and p-MLC protein expressions in UTR knockdown rats decreased markedly compared with that in WT rats." (PMID 29541143, 2018). "Myocardial infarction, ST-segment elevation, and the expression of UTR, ROCK1, ROCK2, and p-MLC protein in rat myocardium were determined at 90 min after reperfusion." (PMID 29541143, 2018). "Finally, to elucidate the mechanism of phenomenon we observed, we found that MFA attenuated HCF differentiation after myocardial infarction by suppressing the migration and proliferation in HCFs, which was by suppressing the pRB-E2F1/CCNE2 and the RhoA/ROCK2 pathway." (PMID 34483923, 2021).